CTLA4 (cytotoxic T-lymphocyte associated protein 4)
Diseases named in the same sentence as CTLA4 in open-access papers (continued):
Sharing a sentence is not in itself a finding about the gene and the disease.
cancer (continued). "Several strategies have been explored of which therapeutic cancer vaccination, adoptive T-cell transfer and more recently blockade of inhibitory receptors such as programmed cell death-1 (PD-1) and cytotoxic T lymphocyte-associated antigen-4 (CTLA-4) have shown promising results." (PMID 27029037, 2016). "The CTLA-4 60G/A polymorphism is a key susceptibility locus for autoimmune and cancer, previous results indicated that presence of G alleles in polymorphic sites 60G/A polymorphism was associated with lower levels of membrane and cytoplasmic CTLA-4 in CD4+ T lymphocytes." (PMID 24376736, 2013). "When CTLA-4 is depleted in cancer cells, the genome becomes unstable due to the reduction of Aurora B expression, then consequently DNA damage occurs accompanied by micronuclei formation in the cytosol." (PMID 41639053, 2026). "Immune checkpoint inhibitors (ICIs) targeting PD-1/PD-L1 and CTLA-4 are widely used in the treatment of several cancers and have significantly improved survival outcomes in responsive patients." (PMID 41749727, 2026). "ICIs, such as anti-PD-1 or anti-CTLA-4 antibodies, are designed to block inhibitory signals that cancer cells use to evade immune detection." (PMID 41355950, 2026). "A variety of immunoregulatory molecules are being explored in order to improve outcomes and overcome resistance to PD‐1/CTLA‐4/LAG‐3 checkpoint inhibition in cancer." (PMID 41474629, 2026). "Conclusively, CTLA-4-depletion induces senescence via genome instability, which activates DNA-PKcs and ultimately leads to cancer growth regression." (PMID 41639053, 2026). "The expression of CTLA-4 early in immune responses can prevent overactivation, whereas its upregulation in chronic infection or cancers contributes to T cell dysfunction." (PMID 41484095, 2026). "Immune checkpoint inhibitors, such as those targeting PD-1 or CTLA-4, can be used to enhance the immune system's ability to attack cancer cells." (PMID 41355950, 2026). "Immune checkpoint inhibitors (ICIs) have transformed modern cancer therapy by restoring antitumor T-cell responses through blockade of immune tolerance pathways such as CTLA-4 and PD-1/PD-L1." (PMID 42064043, 2026). "While monoclonal antibodies targeting PD-L1, PD-1, or CTLA-4 have transformed cancer immunotherapy, resistance to immunotherapy, both primary and acquired, remains a major clinical challenge." (PMID 41486149, 2026). "Immune checkpoint blockade (ICB) has transformed cancer therapy by unleashing CD8+ T-cell activity through targeting the suppression of CTLA-4 and PD-1/PD-L1 signaling pathways." (PMID 41596347, 2026). "Beyond its immune function on T cell surfaces, CTLA-4 is also expressed in various intrinsic cancer cells, where it influences cell proliferation, metastasis, and apoptosis." (PMID 41639053, 2026). "Studies have shown that the delivery of LDR combined with anti-CTLA4 increases the secretion of type I interferon by cancer cells, leading to the recruitment of DCs into the TME." (PMID 40539046, 2025). "In summary, there is good evidence that anti-CTLA-4 mabs have two separate routes to achieving productive cancer immunotherapy, either via TREG depletion or simple blockade of sCTLA-4 or the CTLA-4 receptor." (PMID 40265076, 2025). "The studies and cancer types in this review have shown that treatments targeting PD-1, PD-L1, and CTLA-4 have generally maintained or even improved patients’ HRQL compared with older standards like chemotherapy or targeted drugs." (PMID 41463169, 2025). "LAG-3 is co-expressed and engages in crosstalk with other immune checkpoints, including PD-1 and CTLA-4, in various cancer types." (PMID 39751894, 2025). "Promising research has shown significant improvements in the efficacy of combination therapy involving anti-cytotoxic T-lymphocyte antigen-4 (CTLA-4) and anti-PD-1 antibodies for difficult-to-treat cancer types." (PMID 40746596, 2025).
cancer (continued). "CTLA-4 was the very first immune checkpoint receptor to be clinically targeted, marking the foundational breakthrough in the field of cancer immunotherapy." (PMID 41031910, 2025). "The identification of immune checkpoints such as programmed death-1 (PD-1) and cytotoxic T lymphocyte antigen-4 (CTLA-4) has revolutionized cancer immunotherapy." (PMID 40606673, 2025). "The clinical advancement and identification of ICIs against CTLA-4, PD-1, and PD-L1 have transformed cancer treatments." (PMID 41211067, 2025). "Recently, immunotherapies, particularly immune-checkpoint blockade (ICB) with anti-PD1/PD-L1 and anti-CTLA4, have revolutionized cancer management, offering encouraging survival benefits superior to targeted treatment in a subset of HCCs." (PMID 40051497, 2025). "have been shown to increase the efficacy of both PD-L1 and CTLA-4 immune checkpoint blockade (ICB) therapy in four types of cancers in mice." (PMID 40927726, 2025). "Their ability to reshape the TME, synergize with ICIs (e.g., anti-PD-1 and anti-CTLA-4 therapies), and directly enhance T cell function positions them as powerful tools in the next generation of cancer immunotherapy." (PMID 40927720, 2025). "Monoclonal antibodies targeting the immune checkpoint receptors PD-1 and CTLA-4 are implemented in the treatment of human cancer." (PMID 40271486, 2025). "Collectively, our results confirmed the feasibility and reliability of the predictive mode based on HYP.SIG for assessing response to anti-PD-L1/PD1 or anti-CTLA-4 immunotherapy at the pan-cancer level." (PMID 41419193, 2025). "In conclusion, the exploration of combination immunotherapy involving anti-PD-1 and anti-CTLA-4 agents presents a promising avenue in cancer treatment, demonstrating notable efficacy across various cancers, including CRC." (PMID 41237182, 2025). "Immune checkpoint blockade (ICB) targeting CTLA-4 and PD-1/PD-L1 has revolutionized cancer care, demonstrating significant success in patients with various advanced cancers." (PMID 40390144, 2025). "Antibodies targeting CTLA-4 and PD-1, B7 family co-inhibitory receptors, have elicited durable clinical outcomes in previously refractory cancer types and are considered a breakthrough in cancer therapy." (PMID 40536592, 2025). "High TMB levels have been correlated with improved outcomes in cancers treated with ICIs, such as PD-1/PD-L1 or CTLA-4 inhibitors." (PMID 40333213, 2025). "The combination of PD-1/PD-L1 and CTLA-4 inhibitors has led to significant improvements in clinical outcomes across multiple cancer types, offering enhanced response rates and survival benefits." (PMID 41159031, 2025). "The FDA (Food and Drug Administration) has approved several groups of ICIs to treat a variety of cancers: ipilimumab (CTLA-4 inhibitor); nivolumab, pembrolizumab, and cemiplimab (PD-1 inhibitors); atezolizumab, durvalumab, and avelumab (PD-L1 inhibitors)." (PMID 40561796, 2025). "Anti-CTLA-4 and anti-PD-1 antibodies are immune checkpoint inhibitors that boost immune cells and encourage them to fight cancer." (PMID 41049012, 2025). "Immunotherapy, particularly immune checkpoint inhibitors (ICIs) targeting PD-1/PD-L1 or CTLA-4, has significantly improved cancer treatment outcomes." (PMID 40061961, 2025). "Achieving this goal requires exploring new immune targets alongside the existing star immune targets, PD-1 and CTLA-4, as well as combining drugs to promote an effective immune response to cancer." (PMID 40370819, 2025). "The endosomal deubiquitylase, USP8, interacts with CTLA4, and its loss enhances CTLA4 ubiquitylation in cancer cells, mouse CD4+ T cells, and cancer cell–derived exosomes." (PMID 39404738, 2025). "By binding to CTLA-4, zalifrelimab blocks this inhibitory signal, allowing T cells to remain active and attack cancer cells." (PMID 40739089, 2025).
cancer (continued). "Checkpoint inhibitors, specifically those targeting Cytotoxic T-lymphocyte associated protein-4 (CTLA-4) and Programmed cell death protein-1 (PD-1/PD-L1) pathways, work by blocking the inhibitory signals that cancer cells use to evade immune detection." (PMID 40075661, 2025). "Overall, treatments that target PD-1, PD-L1, or CTLA-4 preserve or even improve the physical, emotional, and social functioning of patients with cancer compared with chemotherapy or observation." (PMID 41463169, 2025). "The success of multiple immune checkpoint therapies, such as anti-PD-1 and anti-CTLA4 antibodies, has resulted in unprecedented responses for a minority of patients with cancer." (PMID 41210994, 2025). "Immune checkpoint inhibitors (ICIs), including anti-PD-1, anti-PD-L1, and anti-CTLA-4 antibodies, have revolutionized cancer immunotherapy by activating cytotoxic T lymphocytes against tumors." (PMID 40860882, 2025). "The PD-1/PD-L1 and CTLA-4 signaling pathways are important immune checkpoint pathways with different mechanisms of action in cancer therapy." (PMID 41369373, 2025). "Checkpoint blockade therapies, such as anti-PD-1 and anti-CTLA-4 antibodies, have revolutionized cancer treatment by reactivating antitumor immunity." (PMID 40755757, 2025). "These ICIs target specific immune checkpoints, including PD-1 and CTLA-4, resulting in an amplified immune response against cancer cells." (PMID 40731762, 2025). "ICB with monoclonal antibodies targeting T‐cell inhibitory molecules such as PD‐1, PD‐L1 and CTLA‐4 has recently emerged as a novel treatment strategy with unprecedented survival benefits for cancer patients, especially for MSI‐H CRC patients." (PMID 40847469, 2025). "In response to v-ATPase inhibition, a pool of CTLA-4 can be secreted from cancer cells via exosomes, presenting its ligand-binding domain to the extracellular milieu." (PMID 41031910, 2025). "Programmed death receptor-1/programmed death receptor ligands-1 (PD-1/PD-L1/PD-L2) and cytotoxic T-lymphocyte-associated antigen-4 (CTLA-4) or HER are among the most common and promising targets for cancer immunotherapy." (PMID 39941799, 2025). "The majority of studies indicate that anti-CTLA-4 antibodies primarily reduce Treg cell numbers in cancer." (PMID 39325360, 2025). "Particularly, PD-1 and CTLA4 inhibitors have been applied in clinical settings, significantly promoting the prognosis of cancer patients." (PMID 40808941, 2025). "Peripheral CD8+ T cell clonal expansion has been found to correlate with the development of severe irAEs in cancer patients treated with CTLA-4 inhibitors." (PMID 40469290, 2025). "Collectively, according to the discussed studies, ICIs have transformed cancer immunotherapy by targeting the CTLA-4 and PD-1/PD-L1 pathways." (PMID 41239350, 2025). "Given the CTLA-4 pathway’s critical involvement in immune evasion, it has emerged as a key target for cancer immunotherapy." (PMID 40739089, 2025). "ICIs are the most thoroughly investigated and critically important immunotherapeutic agents, and the clinical application of PD-1 or PD-L1 and CTLA-4 inhibitors has improved the OS of various patients with cancer." (PMID 39773329, 2025). "For example, pembrolizumab (anti-PD-1) and ipilimumab (anti-CTLA-4) have been approved for the treatment of various cancers, including melanoma and non-small-cell lung cancer." (PMID 40563999, 2025). "Immune checkpoint inhibitors (ICIs), such as CTLA-4 and PD-1 monoclonal antibodies, have demonstrated remarkable clinical efficacy in different types of cancer." (PMID 41437770, 2025). "Hypoxia levels were generally positively correlated with these checkpoint genes, such as CD274 and CTLA4, in various kinds of cancers." (PMID 41419193, 2025). "It kills cancer cells by binding to CTLA-4 on the surface of activated T lymphocytes and stimulating body immune system to launch an attack on cancer cells." (PMID 39923010, 2025).
cancer (continued). "Immune checkpoint inhibitors (ICI), i.e., anti-PD1/PDL1 and anti-CTLA-4, have reshaped the prognosis of many cancers." (PMID 39751892, 2025). "The discovery of novel immune checkpoints has marked a significant advancement in the field of cancer immunotherapy, offering new targets and therapeutic strategies beyond traditional checkpoints like CTLA-4 and PD-1/PD-L1." (PMID 40012016, 2025). "CTLA-4 is mainly viewed as a T cell-specific receptor, but independent studies indicate that it is also present in some cancer cells." (PMID 41031910, 2025). "Cancers with an elevated mutational burden have been observed to demonstrate a greater likelihood of responding favorably to anti-CTLA-4 and anti-PD-1/PD-L1 therapies across a range of cancer types." (PMID 40075727, 2025). "The use of abatacept or the antibody ipilimumab to block CTLA-4 is now a well-established anti-cancer medication, demonstrating the close relationship between IDO1 activation and autoimmune function as well as tumor formation." (PMID 41035912, 2025). "The clinical development of ICIs has transformed cancer treatment, beginning with the approval of ipilimumab, a mAb targeting CTLA-4, over a decade ago." (PMID 40660400, 2025). "Immune checkpoint inhibitors (ICIs), which target key inhibitory pathways such as PD-1/PD-L1 and CTLA-4, have revolutionized cancer immunotherapy by reinstating T-cell activity and overcoming immune evasion mechanisms." (PMID 40165967, 2025). "The development of PD‐1/PD‐L1 inhibitors and CTLA‐4 inhibitors has provided significant and long‐lasting clinical benefits for patients across a spectrum of cancers." (PMID 40787068, 2025). "Various immunotherapeutic strategies have shown substantial promise in treating a wide range of cancers, predominantly involving immune checkpoint inhibitors like PD1, PD-L1, and CTLA4, antibody-drug couplings, and cancer vaccines." (PMID 40406121, 2025). "While a dual-checkpoint blockade targeting PD-1 and CTLA-4 shows promise for advanced cancers, concerns persist regarding inflammatory and autoimmune complications." (PMID 40136857, 2025). "In recent years, ICIs targeting PD-1, PD-L1, or CTLA-4 have emerged as effective treatments for various cancers." (PMID 41561746, 2025). "Emerging evidence highlights the synergistic potential of combining anti-TIGIT antibodies with LAG-3 or CTLA-4 inhibitors in cancer immunotherapy." (PMID 40567374, 2025). "In 1995, Jim Allison and his colleagues identified CTLA-4 as a significant immune checkpoint molecule and proposed it as a potential target for cancer immunotherapy." (PMID 41285707, 2025). "While cytotoxic T lymphocytes (CTLs) have the potential to eliminate cancer cells, their function is often suppressed due to the upregulation of immune checkpoint molecules, such as PD-1 and CTLA-4, a barrier that immunotherapies aim to overcome." (PMID 40333213, 2025). "Currently, commonly used combination immunotherapies include PD1/PD-L1 blockade combined with another ICB, such as anti-CTLA4, or with another cancer treatments, such as chemotherapy and antiangiogenic therapy." (PMID 40038236, 2025). "While ICIs effectively disinhibit PD-1/PD-L1 and CTLA‐4 pathways to attack cancer cells, they can also potentially disrupt immune homeostasis, leading to irAEs." (PMID 39904779, 2025). "ICI, key in IO, enhances antitumor immunity by blocking checkpoints like CTLA-4, PD-1, and PD-L1, allowing T-cells to target cancer cells." (PMID 40260236, 2025). "Recently, the application of immunotherapy involving ICIs, specifically CTLA-4 and PD-1, has shown encouraging results in treating cancer, possibly due to their effect on Tregs and enhanced destruction of Teff cells." (PMID 40224950, 2025). "Clinically approved ICIs include anti–PD-1 antibodies (pembrolizumab, nivolumab), anti–PD-L1 antibodies (atezolizumab), and anti–CTLA-4 antibodies (ipilimumab), all of which have demonstrated durable responses in various cancers." (PMID 41228247, 2025).
cancer (continued). "The anti‐CTLA4 antibody is the first ICI approved for cancer treatment, and several studies have revealed the influence of the anti‐CTLA4 antibody on immune cells through IVM." (PMID 40257446, 2025). "Checkpoint inhibitors (CPIs) like pembrolizumab (anti-PD-1), nivolumab (anti-PD-1), and ipilimumab (anti-CTLA-4), work by blocking these proteins, thereby allowing immune cells (particularly T-cells) to recognize and attack cancer cells more effectively." (PMID 41013821, 2025). "CTLA-4 (CD152), a pivotal immune checkpoint, modulates antitumor immunity by inhibiting immune responses to cancer." (PMID 40677703, 2025). "The advent of immune checkpoint inhibitors, such as anti‐CTLA‐4 and anti‐PD‐1/PD‐L1, has significantly transformed cancer therapy." (PMID 40532063, 2025). "Anti-CTLA-4 antibodies block this interaction, extending T cell responses and promoting cancer cell elimination." (PMID 41285707, 2025). "We further found that ITGA4 was positively correlated with most immune regulatory molecules across cancers, such as CTLA4, PDCD1, LAG3, which inhibit T cell activity." (PMID 40012546, 2025). "Meta-analyses and multi-omics surveys link m6A regulator abundance to CTLA-4 expression patterns across cancers, and Treg- and DC-centric m6A programs plausibly alter the outcomes of CTLA-4 blockade via effects on antigen presentation and Treg stability." (PMID 41280938, 2025). "CIs, including anti-PD1, anti-PD-1L, and anti-CTLA-4, are currently used for cancer immunotherapy and have demonstrated benefits in terms of survival and disease control in several advanced cancers." (PMID 40959088, 2025). "PD-1 and CTLA-4 are co-inhibitory molecules that are highly expressed by Tregs and have been extensively studied to identify novel targets for cancer immunotherapy." (PMID 40650080, 2025). "Immunotherapy utilizing a polysaccharide hydrogel to target checkpoint inhibitors, like CTLA-4 or PD-1/PD-L1, has emerged as an effective therapeutic strategy in cancer treatment." (PMID 40136857, 2025). "It will be important to broaden this kind of exploration to other cancer types and other modalities of immunotherapy including PD-L1 or CTLA-4 blockade, CAR-T cells, oncolytic viruses, or therapeutic vaccination." (PMID 40613596, 2025). "Immune checkpoint inhibitors targeting CTLA-4 and PD-1 have revolutionized cancer therapy by enhancing the immune system's capacity to combat tumors." (PMID 40155973, 2025). "The immunosuppressive effects of CTLA-4 effectively stimulate the immune response, thereby affecting the proliferation of cancer cells." (PMID 39910672, 2025). "Immunotherapy has revolutionized the treatment of human cancers, with immune checkpoint inhibitors (ICIs) such as anti-PD-1/PD-L1 and anti-CTLA4 therapies being extensively utilized in clinical settings for various cancer patients." (PMID 40038776, 2025). "We therefore investigated the impact of CTLA-4 and PD-1 blockade on the selection of developing autoreactive B cells in both cancer patients and humanized mice injected with anti–CTLA-4 and anti–PD-1 mAbs." (PMID 41026527, 2025). "Aside from PD-L1/PD-1 and CTLA-4, a few more immune checkpoint molecules are emerging as key actors in cancer immune evasion." (PMID 40739089, 2025). "For instance, TIGIT, TIM3 and VISTA expression were downregulated in direct co-cultures with LDHC-silenced cancer cells by 72 h, while CTLA-4 expression was reduced in indirect co-cultures." (PMID 40108668, 2025). "Strategies under investigation include combining ICIs with immunogenic cell death inducers; targeting innate immune checkpoints; and integrating mRNA-based cancer vaccines with anti-PD-1, anti-PD-L1, or anti-CTLA-4 antibodies." (PMID 40940902, 2025). "The therapeutic modulation of immune checkpoints, such as CTLA-4 and PD-1, as well as their ligands (PD-L1 and PD-L2), has revolutionized cancer treatment by enhancing T-cell responses against tumors." (PMID 40507229, 2025).